BRAF (B-Raf proto-oncogene, serine/threonine kinase)
Diseases named in the same sentence as BRAF in open-access papers (continued):
Sharing a sentence is not in itself a finding about the gene and the disease.
melanoma (continued). "BRAF mutation and CDKN2A inactivation have been found associated with MITF amplification in melanoma cell lines, but such a correlation was not confirmed in our series." (PMID 29492214, 2018). "Thereafter, anti-PD-1 obtained approval as first-line therapy in all stage IV melanoma patients according to phase-3 trials demonstrating the efficacy of anti-PD-1 regardless of BRAF status." (PMID 29970025, 2018). "BRAF-mutant COADREAD (7.6% of patients) presents a similar problem in that BRAF inhibitor monotherapy is ineffective unlike in BRAF-mutant melanoma and that triple drug combination targeting the EGFR, MAPK, and PI3K pathway has shown more positive results." (PMID 30053901, 2018). "To understand the mechanisms leading to BRAFi-resistant melanoma cells survival in this context, we have generated mouse models bearing human BRAFV600E melanoma cells that mimic clinical relapse and acquired resistance to BRAF inhibitors." (PMID 29487283, 2018). "Although a correlation between BRAF mutation and MITF activation was detected, they did not completely overlap in melanoma cells." (PMID 29950679, 2018). "In summary, we demonstrated that both small molecule SR4 and niclosamide have anti-proliferative and pro-apoptotic activities against melanoma irrespective of BRAF and NRAS status." (PMID 30651927, 2018). "Our data indicate that ABCB5 was overexpressed in BRAF resistant SK-MEL-28PLXr and A2058PLXr melanoma cells but not BRAF-resistant A375PLXr cells." (PMID 29929490, 2018). "Several studies of CTLA-4 and PD-1 therapy have revealed that BRAF V600E mutations do not correlate with either the response to CTLA-4 therapy or the resulting OS, whereas the correlation with the response of melanomas to PD-1 therapy was significant." (PMID 30073150, 2018). "Here, we demonstrate for the first time that Ole treatment represents a new non-toxic anti-cancer agent against BRAF melanoma cells as a suitable promoter of two major agents used in BRAF-resistant melanoma cells, such as RAD001 and DTIC." (PMID 30544808, 2018). "Finally, it was also recently observed that the HIV1-protease inhibitor nelfinavir, was able to sensitize BRAF and NRAS mutant melanoma cells to MAPK-pathway inhibitors." (PMID 29371600, 2018). "Patient 3 is a 58-year old male diagnosed with stage IV, BRAF-negative melanoma of the left ear in 2014 (stage 0) with progression to metastatic disease of the lung in 2016." (PMID 30305172, 2018). "In accordance, we found in this study that the expression of RIP1 was an important mechanism that was involved in intrinsic resistance of melanoma cells to BRAF/MEK inhibitors and played a role in survival of melanoma cells with acquired resistance to BRAF inhibitors." (PMID 29880840, 2018). "Furthermore, it is thought that oncogenic BRAF is resistant to AMPK-mediated inhibition, so ERK signaling cannot be attenuated by AMPK in BRAF mutant melanoma." (PMID 30651927, 2018). "Activation can occur either through a gain of function somatic mutation in BRAF, generating the BRAFV600E substitution mutation found commonly in melanomas arising on non-chronically sun-exposed skin." (PMID 29481571, 2018). "Very interestingly, it was observed that the acquired tumor resistance to BRAF plus MEK inhibition could be reversible, and that patients with BRAFV600-mutant melanoma can respond when rechallenged with dabrafenib plus trametinib." (PMID 29371600, 2018). "MITF is amplified in a subset of human melanomas, which cooperates with oncogenic BRAF V600E to transform normal melanocytes." (PMID 30544544, 2018).
melanoma (continued). "We investigated the functional role of CEACAM1 in a spontaneous metastasis xenograft model of human melanoma in scid mice using BRAF wildtype MeWo cells with and without RNAi mediated knockdown of CEACAM1." (PMID 30089785, 2018). "Unexpectedly, we revealed that in drug-sensitive melanoma cells, BRAFi, in addition to inactivated oncogenic BRAF activity, functions as a non-canonical ligand of AhR." (PMID 30429474, 2018). "BRAF and NRAS mutations (which are important treatment targets in malignant melanoma) are not usually observed in CCS, although there is an exceptional CCS case that harbored BRAF mutation and responded to BRAF-targeted therapy." (PMID 30487384, 2018). "Similarly, a melanoma-specific transcription factor is able to activate HML2 LTRs and the RB protein, a downstream mediator of BRAF–MEK–ERK signaling often altered in cancers, is a key regulator of DNA methylation that can influence HERV expression." (PMID 29593697, 2018). "Having demonstrated the functional importance of RIP1 in protection of melanoma cells from apoptosis induced by BRAF/MEK inhibitors and the mechanism involved, we focused on investigation of the mechanism responsible for upregulation of RIP1 in melanoma cells with acquired resistance." (PMID 29880840, 2018). "Again, neither coexistent BRAF/NRAS mutations nor different mutation frequency distributions between primary and metastatic melanomas were observed." (PMID 29492214, 2018). "These melanoma cells depended on the supply of a BRAF inhibitor and showed a fitness deficit in the absence of vemurafenib leading to regression." (PMID 30344946, 2018). "In this study, we examined interferon-γ (IFNγ) responses in a large panel of immune checkpoint inhibitor-naïve melanoma cells with defined genetic drivers; BRAF-mutant (n = 11), NRAS-mutant (n = 10), BRAF/NRAS wild type (n = 10), and GNAQ/GNA11-mutant uveal melanomas (UVMs) (n = 8)." (PMID 29977240, 2018). "In BRAFi-resistant melanomas however, neither BRAF inhibition nor the combination affected skewness or kurtosis." (PMID 29682188, 2018). "BRAF inhibitors, alone and in combination with MEK inhibitors, significantly reduce the tumor burden and improve the progression-free survival and response rates among advanced melanoma patients." (PMID 30400954, 2018). "In particular, with the recent introduction of the immune checkpoint inhibitors and the new selective tyrosine kinase inhibitors, including BRAF and MEK inhibitors, there has been a significant improvement in the progression-free survival (PFS) and overall survival (OS) of patients with melanoma." (PMID 30154717, 2018). "Seventeen melanoma lines lacked both PD-L1 and PD-L2 basal expression, including 5/10 (50%) BRAF/NRASWT, 4/11 (36%) BRAFV600-mutant, 1/10 (10%) NRAS-mutant, and 7/8 (87.5%) uveal cell lines." (PMID 29977240, 2018). "Interestingly, MYC has been shown to override activated BRAF-induced senescence and partially inhibit NRAS-induced senescence in human normal melanocytes, and depletion of MYC induced senescence in melanomas with activated BRAF/NRAS." (PMID 30526305, 2018). "Although there is no direct nor mechanistic evidence of the MITF-CRYAB transcriptional axis in other cancer types, in melanoma both MITF and CRYAB expression are upregulated by BRAF/MEK-inhibitor treatments, suggesting that this regulation can go beyond both PCa scenario." (PMID 30310055, 2018). "Likewise, BRAF inhibition initially enhanced CD8 (+) T infiltration and reduced immunosuppressive factors in melanoma patients, however, the CD8 (+) T population gradually decreased along with disease progression." (PMID 29455663, 2018). "For this purpose, we used a spontaneous metastasis xenograft mouse model of human BRAF wildtype melanoma cells with and without RNAi mediated L1CAM knockdown." (PMID 29432466, 2018).
melanoma (continued). "It has also been shown that BRAF inhibitor resistance can be mediated by regulatory escape of the transcription factor MITF from the MAPK pathway, where MITF overexpression itself conferred resistance in several melanoma cell lines." (PMID 30349559, 2018). "Our data confirm that PI3K/AKT activation, via gain of function AKT or PIK3CA mutations, promotes the survival, but not proliferative escape, of melanoma cells exposed to dual BRAF/MEK inhibition." (PMID 30237495, 2018). "In this study we investigated choline MRS and parameters obtained from the histogram analysis of the ADC distribution as early markers of response to MAPK targeting via combined BRAF and MEK inhibition, in BRAFV600E vemurafenib-sensitive and resistant melanoma xenografts." (PMID 29682188, 2018). "Given the role of USP28 in the regulation of BRAF and pERK, we investigated the possibility that low USP28 might be a relevant factor in melanoma." (PMID 29880484, 2018). "Our results do indicate that these parameters could be used as early markers of response to the simultaneous targeting of BRAF and MEK in melanoma." (PMID 29682188, 2018). "As we have previously shown, BRAF-mutant melanoma cells were highly sensitive to Gamitrinib; whereas Gamitrinib alone led to 75–80% cell death, the combination with 6-thio-dG did not further enhanced death of BRAF-mutant melanoma cells." (PMID 29695835, 2018). "Moreover, expression of miR-204-5p and miR-211-5p was also enhanced in the BRAF V600E melanoma cell line SK-Mel-28 after treatment with VMF, as well as in 5 out of 6 VMF-resistant clones of the BRAF V600E melanoma cell line SK-Mel-239." (PMID 30460328, 2018). "Melanoma had the highest levels of MAPK activity relative to other tissue types (measured by median MPAS) in our study, consistent with the robust clinical activity of BRAF and MEK1/2 inhibitors observed in this indication." (PMID 29872725, 2018). "As dabrafenib and vemurafenib displayed different activity against BRAF‐ and RAS‐mutant melanoma cell lines, we next asked whether dabrafenib had unique kinase targets." (PMID 29112787, 2018). "A 79 year-old male presented in 2014 with a melanoma on his left cheek (BT 2.4 mm, not ulcerated, BRAF wild-type) with a positive SNB leading to left neck dissection at time of diagnosis (no further positive nodes)." (PMID 30107850, 2018). "Upon CCCP/iron stimulation, pyroptosis was observed in four other melanoma cell lines that expressed GSDME, regardless of the BRAF mutation status." (PMID 30287942, 2018). "In melanoma patients, dual BRAF/MEK inhibition has become standard of care treatment for BRAFV600E/K positive patients due to the prolonged tumor response compared to BRAF inhibitor monotherapy." (PMID 30237393, 2018). "To determine how many patients could potentially benefit from dual inhibition of BRAF and ALK, we analysed the TCGA database focusing on melanoma patients." (PMID 30290811, 2018). "The emergence of some novel therapies against melanoma such as genetically targeted therapies (e.g., BRAF inhibitors) and immunotherapies (e.g., PD-1/PD-L1 and CTLA-4 antibodies) has undoubtedly improved melanoma treatment, but the overall prognosis of patients remains poor." (PMID 29483938, 2018). "The first attempt to monitor ctDNA levels in melanoma patients before and after treatment resulted in a significant positive correlation between the level of remaining detectable serum BRAF V600E and the absence of response to bio/chemotherapy." (PMID 28484715, 2017). "Early trials indicated that around 20% of patients with BRAFV600E mutant melanomas did not respond to BRAF inhibitors." (PMID 29100459, 2017). "Given the obvious cell-cycle arrest and apoptosis induction was observed after combined treatment, BRAF and EZH2 may cooperate in accelerating cell-cycle progression and inhibiting apoptosis to promote melanoma cell growth." (PMID 29202777, 2017).
melanoma (continued). "This intron 8, variant was sufficient to promote the expression of a BRAF transcript lacking exons 4–8 (BRAF exon 4–8∆; also referred to as BRAF3–9) in a single vemurafenib resistant melanoma cell line." (PMID 28503307, 2017). "This strongly suggested that, while CRAF was not able to compensate for BRAF activity during early stages of melanomagenesis, compensatory effects between BRAF and CRAF could rapidly take place in melanoma cells." (PMID 28497782, 2017). "The sensitivity of melanoma cell lines and patient-derived xenograft (PDX) models containing BRAF V600E mutation with or without EZH2 gain to vemurafenib (BRAF inhibitor), GSK2816126 (EZH2 inhibitor) and a combination of both agents was evaluated." (PMID 29202777, 2017). "CpG microarray analysis of UACC62 melanoma cell lines with and without BRAF knockdown surprisingly identified many hypermethylated and hypomethylated genes, suggesting that mutant BRAF dictates a specific methylation program." (PMID 28396701, 2017). "Briefly, A375 melanoma cells grown in light medium without serum were treated with Vemurafenib (BRAF inhibitor) and Trametinib (MEK1/2 inhibitor), while cells grown in heavy medium without serum were treated with vehicle." (PMID 28387310, 2017). "CJM, HMCB, and CHL1 also lacked mutations in BRAF, NRAS, or NF1, but these cell lines had similar FGA and mutational burden relative to other melanoma cell lines as well as tumors." (PMID 29383127, 2017). "Recently, the Food and Drug Administration (FDA) approved nivolumab (Opdivo), a PD-1 immune checkpoint inhibitor, for the treatment of advanced (unresectable or metastatic) melanoma in adults, regardless of BRAF status." (PMID 28445515, 2017). "While MAPK and AKT signaling play an important role in melanoma progression, it is currently not clear what other pathways suppress oncogene-induced stress in BRAF mutant cells to allow them to proliferate." (PMID 28753606, 2017). "The MEK inhibitor PD0325901 has also demonstrated efficacy in melanoma cell lines independent of BRAF status." (PMID 28187762, 2017). "Also, when tested in mice with melanoma xenografts, PET-16 enhances the durability of response to BRAF inhibition." (PMID 28484090, 2017). "This notion is supported by pre-clinical findings that BRAF inhibitor therapy can enhance IFNγ production, T cell proliferation and MHC expression by melanoma cells, and by clinical evidence of increased tumor-infiltrating lymphocyte populations during BRAF inhibitor therapy." (PMID 29100459, 2017). "Choosing the most effective treatment for patients with BRAF‐WT melanoma who have not responded or are ineligible for immunotherapy remains a clinical challenge." (PMID 28719152, 2017). "Polysomy of NRAS/chromosome 1 was detected in 13.3% (4/30) of HET, and 28.6% (6/21) of High non-HET samples, but was absent in BRAF/NRAS WT melanomas (P < 0.05)." (PMID 28668077, 2017). "However, at the end of the treatment, we observed the emergence of resistant clones that enabled us to establish double BRAF and CRAF KO melanoma cultures." (PMID 28497782, 2017). "In melanoma, both MEK and BRAF inhibition led to an induction of Ets-1 and NRAS expression that could be blocked by Usp9x inhibition." (PMID 28198367, 2017). "Here, we applied single-cell RNA-seq to measure the transcriptomes of 307 single cells cultured from three biopsies of three different patients with a BRAF/NRAS wild type, BRAF mutant/NRAS wild type and BRAF wild type/NRAS mutant melanoma metastasis, respectively." (PMID 27903987, 2017). "The other mutated case was an acral melanoma diagnosed in 2009, displayed a -124:G>A TERT promoter mutation, but not a BRAF mutation; the patient died 24 months after diagnosis, in line with the poor prognosis of CM harbouring TERT promoter mutations." (PMID 28662141, 2017).
melanoma (continued). "The inclusion of TERT promoter mutations within ctDNA for monitoring would increase the number of patients for whom ctDNA could be used to determine disease status, particularly amongst BRAF and NRAS wild-type melanoma patients." (PMID 29108273, 2017). "Based on these findings, they suggested that treatment of BRAF-mutant melanomas with a combination of a BRAF inhibitor and an AMPK activator (phenformin) could offer therapeutic advantages over BRAF inhibitor (BRAFi) single agent therapy." (PMID 29371951, 2017). "In summary, these findings add significant and novel mechanistic insight into the potential role of HGF/MET signaling in mediating resistance to BRAF and MEK inhibitors and support the clinical evaluation of MET kinase inhibitors and HGF-neutralizing antibodies in melanoma." (PMID 28147313, 2017). "These are predominantly attributed to MAPK pathway activation and increased Ras activity in BRAF wild-type cells exposed to BRAF inhibitors, adding a cautionary note to avoid BRAF inhibitor therapy in melanoma patients without mutant BRAF status." (PMID 29179523, 2017). "Moreover, in BRAFmut melanoma, combination of an AKT inhibitor with a BRAF-selective inhibitor reportedly reversed the resistance to either inhibitor." (PMID 27999210, 2017). "For example, a recent study reported that KD increased tumor cell proliferation in BRAF positive melanoma but not in BRAF negative melanoma cells, confirming that KD has different effects depending on the type and genetics of a tumor." (PMID 28915665, 2017). "To investigate the molecular mechanisms underlying this differential requirement of RAF kinases at different stages of melanomagenesis, we used in situ proximity ligation assays (PLA) to look at the ability of endogenous BRAF and CRAF to interact with NRAS first in cells from full-blown melanoma." (PMID 28497782, 2017). "This hypothesis was tested in BRAF mutant SKMEL28 human melanoma cells following treatment with the Hsp90 inhibitor 17-AAG and the BRAF inhibitor vemurafenib." (PMID 28811486, 2017). "Somatic mutations in the oncogene RAF1 are remarkably rare in human cancers; however, in BRAF negative melanomas, targeting RAF1 leads to apoptosis." (PMID 27993549, 2017). "Both BRAF and NRAS mutations are predictors of poorer outcome and lower overall survival (OS) of patients than those with nonmutated melanoma." (PMID 28484715, 2017). "In our one relapsing patient who did not respond to RAF inhibition, the recurrent melanoma was found to be BRAF WT by next-generation sequencing." (PMID 29285228, 2017). "The unique role of HGF/MET signaling in conferring resistance to MAPK pathway inhibitors in BRAF and NRAS mutant melanoma suggests that combination therapy with small-molecule MET inhibitors may provide additional benefit beyond BRAF and MEK inhibitors alone." (PMID 28147313, 2017). "Finally, we show that the combination of BRAF inhibitors with PDK inhibitors is more efficient in tumor growth suppression than the single treatment suggesting that the simultaneus targeting of metabolic pathways might indeed be beneficial for melanoma patients." (PMID 28595656, 2017). "The patient had an excision of a primary melanoma of the thigh 15 years earlier but the BRAF status had not been determined." (PMID 28743309, 2017). "While nearly 50% of melanoma patients usually respond to BRAF inhibitors, the number of non-responding patients decreased by 40% when BRAF inhibitors were used along with MEK inhibitors as a combination therapy." (PMID 28567163, 2017). "Although the development and clinical trial of selumetinib has focused on KRAS-mutant non-small-cell lung cancer or BRAF-mutant melanoma, it is not clear that MEK inhibitors are specific for KRAS-mutant cancers." (PMID 29296181, 2017).